MIF (macrophage migration inhibitory factor)
Diseases named in the same sentence as MIF in open-access papers (continued):
Sharing a sentence is not in itself a finding about the gene and the disease.
Insulin resistance (continued). "In the pancreas, adipose tissue, and muscle cells, the pleiotropic characteristics of MIF are reflected in the different routes that lead to insulin resistance." (PMID 24527464, 2014). "MIF represents a potential therapeutic target for treatment of high-fat diet induced insulin resistance." (PMID 25412423, 2014). "MIF contributes to regulation of glucose metabolism and is involved in development of insulin resistance." (PMID 23536817, 2013). "The high glucose levels that occur in insulin resistance states, oxidize the low-density lipoproteins which in turn have been shown to activate NF-Kβ and induce MIF expression, in vascular smooth muscle cells." (PMID 21143928, 2010). "EVs enriched with IL-6, Monocyte Chemoattractant Protein-1 (MCP-1), and macrophage migration inhibitory factor (MIF), originating from the adipocytes of patients with aneurysmal aortic disease, have been shown to induce systemic insulin resistance and correlate positively with liver enzyme levels." (PMID 40129979, 2025). "High fat diet induced adipose MIF release is positively associated with insulin resistance in the presence or absence of adipose inflammation." (PMID 37935315, 2024). "PAR2 activation induced MIF secretion is associated with the increase of P115 expression in a non-inflammatory mechanism of insulin resistance." (PMID 39416784, 2024). "Moreover, we did not assess insulin resistance markers, such as homeostasis model assessment of insulin resistance, and inflammatory markers (MIF, TNF-α, and IL-6)." (PMID 30563254, 2018). "Relationship between (plasma) MIF and insulin resistance/T2D." (PMID 26124760, 2015). "Additionally, we showed that MIF is important to the production of some adipocytokines such as resistin, which is the most important adipocytokine in the development of insulin resistance." (PMID 24527464, 2014). "Furthermore, MIF also stimulates the production of certain inflammatory adipocytokines, such as resistin and IL-6, which are key molecules in the development of insulin resistance." (PMID 24527464, 2014). "While a role for MIF could be demonstrated in various settings of experimental type I diabetes, the involvement of MIF in the pathogenesis of insulin resistance/T2D has hardly been explored." (PMID 20169173, 2010). "However, positive correlation of MIF with TG/HDL-C ratio might reflect an induction of MIF by high FFA which characterizes the insulin resistance and T2DM." (PMID 27298517, 2016). "Since epidemiological studies have shown both insulin resistance and NAFLD to be associated with future CVD risk, this may also have relevance for the role of MIF in vascular disease, which has been described elsewhere for rodents and humans, and will not be addressed here." (PMID 26124760, 2015). "The macrophage migration inhibitory factor (MIF) is an immunoregulatory mediator expressed in tissues and involved in the modulation of dysmetabolic effects including insulin resistance, glucose, and FFA metabolism." (PMID 36147562, 2022). "Similar to the circulating levels of MIF in women with GDM, placental MIF expression is increased in GDM and this correlates with maternal insulin resistance." (PMID 33923959, 2021). "We only demonstrated that both insulin resistance and an increase in serum MMP-9 and MIF coexist in the group of subjects with family history of T2D." (PMID 30302090, 2018). "The two groups were well matched for BMI and circulating levels of biomarkers involved in glycaemic control, indices of insulin resistance, inflammation (IL-6, CRP, TNF-α, MIF), oxidative stress and SpO2." (PMID 24733551, 2014). "We recently showed that genetic deletion of MIF reduces systemic inflammation (SAA and fibrinogen) and protects mice against the development of glucose intolerance and insulin resistance." (PMID 20169173, 2010).
Insulin resistance (continued). "IL-1, IL-6, MIF (macrophage migration inhibitory factor) and TNF-α induce insulin resistance, have cytotoxic actions, are neurotoxic, and seem to have a role in the pathobiology of cardiovascular and neurologic and psychiatric conditions." (PMID 20042103, 2009). "CPZ-induced insulin resistance appeared to be associated with increased plasma glucose levels rather than insulin levels, in contrast to the insulin resistance induced by MIF." (PMID 38802393, 2024). "Studies have also shown that adipocytes could regulate insulin resistance in hepatocytes by secreting EVs carrying miR-141-3p, monocyte chemoattractant protein-1 (MCP-1), IL-6, and macrophage migration inhibitory factor (MIF)." (PMID 39697630, 2024). "Taken together, these findings indicated that the tautomerase activity-lacking of MIF improved insulin resistance." (PMID 32265835, 2020). "Inhibition or knockdown of MIF or its receptor CD74 could improve the glucose tolerance and insulin resistance, even ameliorate hepatic steatosis induced by HFD." (PMID 32265835, 2020). "In our study, we did not observe a relationship between the concentration of MIF and insulin resistance." (PMID 30302090, 2018). "Moreover, MIF is a necessary mediator of TNF-α, which inhibits the insulin signal transduction leading to insulin resistance." (PMID 27298517, 2016). "Contrary to other reports, we did not detect any MIF inhibition-induced improvement of fasting blood glucose, glucose intolerance, insulin resistance or dyslipidemia." (PMID 23536817, 2013). "In addition, the insulin resistance and type-2 diabetes were characterized by an increase in lipolysis and FFA concentrations, and elevated FFA levels also induced an increase in MIF." (PMID 21283592, 2011).
prostate carcinoma (45 papers, 2003 to 2025). A carcinoma that arises from epithelial cells of the prostate gland. "MIF promotor polymorphisms are associated with worse survival in prostate cancer, with the -173 G/C SNP correlating with increased disease incidence and -794 CATT7 correlating with an increased 5-year recurrence risk." (PMID 38732068, 2024). "In prostate cancer patients, MIF expression is highly elevated, which has been associated with higher severity and poor outcome." (PMID 36496973, 2022). "In particular, as evidence of the association between T. vaginalis infection and prostate cancer, macrophage migration inhibitory factor (MIF) secreted from T. vaginalis has been reported to induce proliferation of prostate cancer cells." (PMID 32196489, 2020). "Macrophage migration inhibitory factor (MIF) is a cytokine associated with prostate cancer, based on histologic evidence and circulating (serum) levels." (PMID 16000172, 2005). "The macrophage migration inhibitory factor (MIF) gene was reported to be elevated in prostate cancer tissues and upregulation of this gene is associated with serum level of MIF." (PMID 12671711, 2003). "The contribution of the MIF alleles in the progression of cancer was correlated and reported in different types of cancers such as hepatocellular carcinoma, gastric cancer, BC, and prostate cancer." (PMID 38916819, 2024). "Given the role of MIF in several cancers, including ccRCC, and its use as a diagnostic marker for prostate cancer, identifying the mechanism could yield potential therapeutic targets." (PMID 26741693, 2016). "This discrepancy is worth investigating since establishing the exact role of MIF in prostate cancer may prove useful as a diagnostic or prognostic indicator (in addition to the well-established standard, prostate specific antigen – PSA) for this important disease entity." (PMID 16000172, 2005). "A number of monoclonal antibodies targeting MIF have been developed; BaxB01, BaxG03, and BaxM159 induced apoptosis in prostate cancer cells in-vitro by inhibiting ERK1/2 signaling, leading to reduced tumor growth in a xenograft mouse model." (PMID 41159021, 2025). "Our findings suggested that EAF2 was involved in the infiltration of CD163-positive macrophages in prostate cancer via MIF." (PMID 38969982, 2024). "Low miR-451 expression independently predicts worse disease-free and overall survival in CRPC; conversely, enhanced expression in prostate cancer cell lines reduces growth, migration, and invasiveness, negatively correlating with MIF." (PMID 38732068, 2024). "Chronic T. vaginalis infections result in TvMIF (T. vaginalis macrophage migration inhibitory factor)-driven inflammation and cell proliferation, thus triggering pathways that contribute to progression of prostate cancer." (PMID 36864428, 2023). "Altogether, these findings indicate MIF is part of the signaling response of BM macrophages to the engulfing of apoptotic prostate cancer cells and suggests a network connection with the activation of hypoxia-related molecules by efferocytosis." (PMID 36496973, 2022). "MIF changes were investigated in the overall macrophage population co-cultured with apoptotic RM1 prostate cancer cells by RT-qPCR and Western blot analysis." (PMID 36496973, 2022). "Correlation between expression of MIF and E-cadherin and clinicopathological features of prostate cancer." (PMID 34157052, 2021). "The half-life of MIF secreted by normal prostate cells has been reported as 9 h, with an increased stability when secreted from prostate cancer cells resulting in a half-life of 36 h." (PMID 30475854, 2018). "Lower expression level of HBP1 resulted in the increased expression level of MIF gene (macrophage migration inhibitory factor) and promoted the ability of colony formation and invasion of prostate cancer cells." (PMID 26942107, 2016).
prostate carcinoma (continued). "Several groups have shown a correlation between MIF expression and cancer prognosis in hepatocellular carcinomas, colon and prostate cancers." (PMID 26883190, 2016). "Taken together, our data confirm that (total) MIF levels were significantly upregulated in the plasma of patients with solid tumors, such as ovarian cancer or prostate cancer." (PMID 27636991, 2016). "Similar observations have been made using siRNA targeting of MIF in prostate cancer and ovarian cancer cells." (PMID 25015194, 2014). "The primary outcome of the study is a change in prostate cancer relevant cytokines and hormones (IL-6, MIF, IGF-1, Testosterone)." (PMID 23731674, 2013). "Two recent studies described an association between higher MIF producing genotypes (greater number of CATT repeats) and gastric and prostate cancer respectively." (PMID 22168770, 2011). "It has been reported that MIF expression is correlated with cancer prognosis, specifically for hepatocellular carcinomas, colon cancers and prostate cancers." (PMID 21283538, 2011). "We also recently observed in vitro that reducing CD74 mRNA (using RNA interference) upregulated MIF in prostate cancer cells." (PMID 19503733, 2009). "Similar obeservation have been made using siRNA targeting of MIF in prostate cancer and ovarian cancer cells." (PMID 20038293, 2009). "MIF overexpression has been observed in various human cancer tissues, including colorectal, breast, lung, bladder and prostate cancer." (PMID 17640378, 2007). "Addition of MIF to proliferating DU-145 prostate cancer cells resulted in a twofold increase in the relative amount of active MMP-2." (PMID 16872482, 2006). "The alternative explanation for reduced MIF immunostaining is supported by the data presented here, namely, there is increased MIF secretion by aggressive prostate cancer cells." (PMID 16000172, 2005). "Increased MIF mRNA expression was observed in prostatic adenocarcinoma compared to benign tissue from matched samples, supporting our earlier finding of increased MIF gene expression in prostate cancer." (PMID 16000172, 2005). "It is possible that a similar mechanism accounts for the increased MIF secretion by prostate cancer epithelial cells and increased MIF serum levels in cancer patients." (PMID 16000172, 2005). "Analysis of the resulting band intensities documents an 8 to 12 fold increase in MIF amounts secreted by prostate cancer cell lines compared with normal prostate cells." (PMID 16000172, 2005). "This laboratory was first in localizing MIF within prostatic epithelium and in establishing that MIF is consistently increased within both prostate tissue and serum in prostate cancer patients." (PMID 16000172, 2005). "Increased secreted MIF was detected in culture medium from prostate cancer cell lines (LNCaP and PC-3)." (PMID 16000172, 2005). "Our findings suggest that EAF2 may facilitate the accumulation of macrophages within prostate cancer tissue through MIF-mediated mechanisms." (PMID 38969982, 2024). "Our results indicated that the downregulation of EAF2 in prostate cancer may increase the accumulation of macrophages by promoting the production of migration inhibitory factor (MIF)." (PMID 38969982, 2024). "Similarly, BM macrophages isolated from FVB mice upregulated MIF protein upon the efferocytosis of Myc-CaP prostate cancer cells." (PMID 36496973, 2022). "Aberrant expression of MIF protein was observed also in many other types of cancers, such as colon, melanoma, glioblastoma, lung adenocarcinomas, renal cancer, urothelial cancer, pancreas carcinoid, thyroid cancer as well as prostate cancer." (PMID 34157052, 2021). "Our results seem promising and strongly highlight the potential role of MIF in development of nodal metastases as well as may confirm an involvement of β-catenin in disease spread in case of prostate cancer." (PMID 34157052, 2021).
prostate carcinoma (continued). "MIF can function as a modulator of important cancer-related genes expression, as well as an activator of signaling pathways that promotes the development of prostate cancer." (PMID 34157052, 2021). "Moreover, we found that upregulation of the cytoplasmic MIF, produced by the prostatic cancer epithelium, participates in the infiltrating of both the right and left zone of prostate cancer gland." (PMID 34157052, 2021). "Furthermore, the anti-MIF monoclonal antibodies were effective in vitro and in vivo in prostate cancer and colon cancer models." (PMID 32155795, 2020). "A reduction of tumor growth was also observed in sub-cutaneous human neuroblastoma and prostate cancer xenografts, after inhibition of MIF expression by MIF antisens transfection or RNA interference or after treatment with anti-MIF antibodies or MIF inhibitors." (PMID 26883190, 2016). "In prostate cancer, MIF was intense but CD74 staining was weak and patchy." (PMID 24939415, 2014). "Thus, we proposed that MIF, a proinflammatory cytokine constitutively expressed by the prostatic epithelium and upregulated in prostate cancer, plays an important role in this disease entity." (PMID 16000172, 2005). "The expression of CD74 in the human prostate or its association with prostate cancer has not been investigated, but if MIF affects prostate cancer cell growth, then it is predicted that MIF's receptor should be localized within prostate tissue." (PMID 16000172, 2005). "However, prostate cancer cells (LNCaP and PC-3) showed significantly greater MIF secretion when compared to the normal cell line." (PMID 16000172, 2005). "Our recent paper established that patients with prostate cancer had elevated serum MIF levels." (PMID 16000172, 2005). "Based upon these findings it is tempting to speculate that the increased MIF secretion by prostate cancer cells is responsible for the increased serum MIF levels observed in prostate cancer patients." (PMID 16000172, 2005). "Therefore, it is hypothesized that EAF2 may not only have a direct effect on tumor cells but also an indirect effect through the recruitment of macrophages mediated by MIF, promoting prostate cancer progression." (PMID 38969982, 2024). "Moreover, increased MIF expression in prostate cancer has been independently documented by other laboratories, further supporting our hypothesis." (PMID 16000172, 2005). "Previous studies highlight the critical role of MIF and its interactions with chemokine receptors CXCR7 and CXCL12 in tumor growth, prognosis, and treatment of prostate cancer." (PMID 41159021, 2025). "CD74 was found to be overexpressed in prostate cancer cell DU145, as compared with normal prostate cells, and blocking interaction of MIF with CD74 selectively inactivated ERK1/2, leading to reduced prostate cancer cell proliferation and increased apoptosis." (PMID 38874510, 2024). "This coincides with observations of MIF and CXCR7 overexpression in prostate cancer tissues and in vitro models, including castration-resistant prostate cancers (CRPC)." (PMID 38732068, 2024). "The MIF/CXCR7/AKT pathway drives growth and metastasis in castration-resistant prostate cancer cells." (PMID 36042480, 2022). "We found that BM macrophages engulfing apoptotic prostate cancer cells promoted HIF-1α stability and subsequent HIF-1α and p-STAT3 nuclear translocation to induce the expression of the pro-inflammatory cytokine MIF." (PMID 36496973, 2022). "In correspondence with the identified mechanism, the efferocytosis of apoptotic prostate cancer cells induced a more robust activation of STAT3 and MIF expression compared to the efferocytosis of apoptotic normal cells." (PMID 36496973, 2022). "In prostate cancer, HBP1 directly targeted the MIF promoter and inhibited its transcription, which remarkably blocked cell growth and invasion." (PMID 29367693, 2018). "Previously, Meyer-Siegler and coworkers showed a positive correlation between MIF and MMP-2 in prostate cancer cells." (PMID 16872482, 2006).
prostate carcinoma (continued). "In addition, macrophage migration inhibitory factor (MIF), a pro-inflammatory factor that is critical in the onset and progression of intestinal, breast, and prostate carcinoma among other malignant tumors, induces EMT in cancer cells." (PMID 38515577, 2024). "The anti-MIF monoclonal antibodies BaxG03, BaxB01, and BaxM159 have been developed at Baxter (now Shire) that have shown potent dose-dependent in vitro and in vivo chemotherapeutic effects in human PC3 prostate cancer cells." (PMID 29707160, 2018). "A fully human anti-MIF antibody which does not distinguish between redMIF and oxMIF failed to exert a significant beneficial effect in a mouse xenograft prostate cancer model (results not shown)." (PMID 27636991, 2016). "We determined MIF serum levels in normal (non-CaP) and prostate cancer (CaP) patients using milk based buffer as the ELISA blocking agent and sample diluent." (PMID 16000172, 2005). "Serum MIF levels were significantly increased, even in this small sample, when we used the milk-diluent based MIF ELISA (our protocol), with non-CaP having 4.18 ± 0.99 ng/ml compared to prostate cancer patients that had 13.06 ± 6.15 ng/ml of MIF in the serum." (PMID 16000172, 2005). "Median serum MIF amounts were significantly elevated in prostate cancer patients (5.87 ± 3.91 ng/ml; ± interquartile range; n = 115) compared with patients with no documented diagnosis of prostate cancer (2.19 ± 2.65 ng/ml; n = 158)." (PMID 16000172, 2005). "However, MIF-induced activation of EMT has not been confirmed in prostate cancer patients." (PMID 34157052, 2021). "Whether increased serum MIF has predictive value that is independent of known predictive markers such as rising PSA values or Gleason score in prostate cancer awaits a larger trial that compares these variables prospectively with PSA levels and patient outcomes." (PMID 16000172, 2005).